IRF1 (interferon regulatory factor 1)
Diseases named in the same sentence as IRF1 in open-access papers (continued):
Sharing a sentence is not in itself a finding about the gene and the disease.
infection (continued). "Overexpression of IRF7 in KO IFNAR1 cells infected with DTMUV partially restored the expression of IFN-β at 12–48 hpi, IFIT5 at 36–48 hpi, IRF1 at 48 hpi, and MX1 at 12–48 hpi, indicating a type I IFN-independent role of IRF7 in the induction of these genes during DTMUV infection." (PMID 35891486, 2022). "While IRF1 again showed no notable effect on IFN-β or -λ induction upon virus (RVFV) infection and only minimally increased IFN-α, its overexpression inhibited the replication of all four tested viruses, underscoring its capacity to induce direct antiviral effects." (PMID 34685580, 2021). "Subsequently, we assessed whether IRF1 influences the negative modulation of the Th1 immune response during infection." (PMID 32210480, 2020). "When the same experiment was performed with H. hammondi sporozoites, prior infection failed to suppress IFNγ-induced IRF1 activation, suggesting that sequence differences in the IST locus may determine species-specific differences in the host response." (PMID 32574210, 2020). "In addition, infection with L. infantum significantly induced the development of IFN-γ-producing CD4+ T cells, in terms of both percentage and total cell number, in both the WT and Irf1−/− mice compared to their counterparts." (PMID 32210480, 2020). "Infection by the ∆Npro mutant did not affect poly(I:C)-induced IRF1 mRNA level (P > 0.05)." (PMID 31683525, 2019). "Furthermore, with increased K48 ubiquitination, IRF-1 protein levels dramatically decreased, whereas this reduction was absent when infection was performed in the presence of MG132 (bottom blots and graphs)." (PMID 27795392, 2016). "To delineate the effect of FV1 lpg1− and/or FV1 lpg2− on the upstream transcriptional features that regulate IL12B expression, we assessed IRF1 expression in hDCs and observed that infection with FV1 mutants up-regulated IRF1, but not significantly more compared to WT induced levels." (PMID 26630499, 2015). "No IFN-α was detectable in WT and IRF-1−/− mice from day 4 post infection." (PMID 24675692, 2014). "Of the 14 Th1 response genes tested, the expression levels of 8 genes (IL2, IFNG, CSF2, TLR4, CD4, IRF1, SOCS5 and STAT4) were significantly elevated at 2 weeks and several of these (IL2, IFNG, TLR4, CD4 and STAT4) had similar expression levels at 4 and 8 weeks post-infection." (PMID 23448601, 2013). "We next determined IRF1 levels after infection in the absence of IFNγ." (PMID 23240025, 2012). "Thus, IRF-1 restricts WNV tissue tropism and modulates infection in peripheral tissues." (PMID 21909274, 2011). "Moreover, prior infection of the macrophages with C. pneumoniae did not alter the ability of IFNγ to induce IRF-1 in BMDM of both genotypes." (PMID 22096480, 2011). "Importantly, the polarization phenotype of U937 macrophages did not change drastically after 8h of infection, although we detected a statistically significant reduction (~30%) in IRF1 expression, concomitant with a ~40% increase in IL-10 in M1 polarized macrophages as compared to M0 controls." (PMID 38808065, 2024). "In WT infection at 48 hpi, we detected pSTAT1 bound at both site 1 and 2 upstream of UL138 relative to the uninfected IRF1 control, whereas we did not detect binding of STAT1 to these sites in ΔUL138STOP infection." (PMID 37289831, 2023). "The transcription factors IRF1 and IRF2 mediate non-canonical inflammasome activation by driving the expression of CASP4 and GSDMD genes at steady state and during infection." (PMID 38106412, 2023). "By contrast, AIM2-dependent inflammatory responses to the infection with the gamma herpesvirus murine cytomegalovirus (MCMV), or transfection of double-stranded DNA does not require IRF1." (PMID 33476326, 2021). "On the other hand, there was no distinct trend between infection with CVI988 and vvRB1B and the expression of cytokines and chemokines, such as IL-10, IFN-γ, STAT1, IRF1, CCL19, and CCL26." (PMID 32210095, 2020).
infection (continued). "This is consistent with methyl-cytosines remaining unchanged during bisulfite treatment, and the notion that CpGs within the irf1 promoter are largely non-methylated in RAW264.7 cells before and after infection with T. gondii." (PMID 33072127, 2020). "In spleen cells, the IFN-γ expression level was up-regulated at 4 weeks after M. avium infection; however, the expression levels of IRF-1-, IRF-2- and Sca-1-, and IFN-γ-responsive genes did not increase or decrease until 4–12 weeks after infection." (PMID 29259694, 2016). "Cellular infiltrate was quantified over the course of infection, which showed a significant increase in total cells resident in the lungs on day 7 postinfection in IRF7−/− mice but not in IRF1−/− mice (P < 0.05)." (PMID 27822537, 2016). "Using this system, we observed the expression of IRF-1 but not IRF-2, a repressor of CEACAM1 transcription and other target genes, 12 h after infection with an apparent peak at 24 h." (PMID 24650050, 2014). "This suggests that macrophages can restrict WNV-NY infection through an alternative pathway that is independent of IRF-3, IRF-5, and IRF-7, possibly through IRF-1 and/or other transcription factors." (PMID 23300459, 2013). "Compared to the corresponding protein level measured in uninfected cellular extracts, the infection performed with P. gingivalis at a MOI of 100 significantly reduced the expression level of SOCS-3 (5-fold), IRF-1 (5-fold), and EGFR (6-fold), but not STAT-3, in the nuclear extracts." (PMID 28748038, 2017). "Although IRF1 and IRF8 are known to cooperatively regulate IL12B gene transcription, we report that the FV1 lpg1− mutant does not affect IRF1 expression compared to WT at 8 hours post-infection." (PMID 26630499, 2015). "The function of IRF-1 is non-redundant to type I IFN activity and the slightly higher concentrations of IFN-β in IRF-1−/− mice are possibly induced by increased viral load or immune cells activation but still succumb the infection." (PMID 24675692, 2014). "The down-regulation of genes involved in the interferon response (i.e. irf1, irf4 or irf8) in infected samples at 7 dpi (and lack of up-regulation of other interferon genes at this time point) suggests that ISAV modulates this process as part of its infection and replication strategy." (PMID 33985436, 2021). "Considering the rapidity by which translational repressor 4E-BP1 is inactivated (within an hour) and the ability of RSVA2 to negate the effects of MEKi on ISGs (i.e. IRF1), these events might partly explain the absence of positive modulation of IFNL1 gene following RSVA2 infection." (PMID 31319869, 2019). "The results showed that infection of HGEC cells with P. gingivalis, but not with heat-killed P. gingivalis, led to significant reductions in expression levels of mRNAs and proteins for SOCS-3, IRF-1, and EGFR, while LPS-Pg over time significantly increased the expression of these mRNAs and proteins." (PMID 28748038, 2017).
cancer (208 papers, 2009 to 2025). A tumor composed of atypical neoplastic, often pleomorphic cells that invade other tissues. "Surprisingly, and in contrast to the well-established antiproliferative role of IRF-1 in cancer, B cell-specific IRF-1 deficiency resulted in decreased proportion of Ki-67+ germinal center B cells." (PMID 41263556, 2025). "For rs2070721, rs3740688 and rs4788115, the allele that increased cancer risk also increased expression of IRF1, SPI1 and LAT, respectively, in the eQTLGen data." (PMID 40428397, 2025). "Mutations in the IRF1 gene or changes in its function have been linked to several types of cancer 146,147." (PMID 38169587, 2024). "The epigenetic activity of transcription factor motifs linked to cancer immunogenicity, e.g., Irf1/2/8/9, Stat1, and Nfkb1, were increased in KO cells, which coincided with findings in a PRRX1-overexpressing cell line model." (PMID 39255035, 2024). "They found that cancer-associated SPOP mutations result in diminished IRF1 degradation, and consequentially increased expression of the IRF1-driven immune-suppressive PD-L1." (PMID 37622993, 2023). "Of note, our single-cell sequencing analysis revealed that IRF1 was highly expressed mainly on endothelial cells, myoepithelial cells, and cancer-associated fibroblasts, while relatively low expression was observed in cancer cells and peripheral immune cells." (PMID 36226063, 2022). "IRF-1 has been implicated in the upregulation of stress-induced apoptosis and downregulation of invasive activity in different cancer cells." (PMID 35092496, 2022). "IRF-1 upregulation in UC-associated dysplasia/colitic cancer was significantly associated with CD8 (P = 0.032) and γH2AX (P = 0.001) upregulation." (PMID 34158547, 2021). "The present findings showed that PD-L1 expression in UC-associated dysplasia/colitic cancer was positively correlated with γH2AX and IRF-1 expression." (PMID 34158547, 2021). "The different mechanisms underlying IRF-1 inactivation and their implications for human cancers and the potential importance of IRF-1 in immunotherapy are also summarized." (PMID 29599126, 2018). "First, IRF1 expression is indispensable for BV6-induced cell death in a panel of cancer cell lines, as siRNA-mediated depletion of IRF1 significantly rescues cells from BV6-induced loss of cell viability and apoptosis." (PMID 25501823, 2014). "The high frequency of mutated or rearranged IRF-1 in several cancer types indicates its importance in oncogenesis." (PMID 23420765, 2013). "While the exact underlying mechanisms are not fully understood, it was suggested that IRF1 deficiency may lead to inefficient induction of apoptosis in cancer cells." (PMID 37889967, 2023). "IRF-1 has been implicated in the response of cancer cells to cisplatin." (PMID 35092496, 2022). "Furthermore, PD-L1 expression was significantly associated with high levels of tumoural CD8+ CTLs, γH2AX as a DSB marker, and IRF-1 as a transcriptional factor for PD-L1 in UC-associated dysplasia/colitic cancer compared with SCRC." (PMID 34158547, 2021). "Moreover, PD-L1 upregulation was associated with γH2AX (DSB marker) and IRF-1 upregulation in UC-associated dysplasia/colitic cancer." (PMID 34158547, 2021). "Previous clinical studies have indicated that loss of IRF-1 may affect development of specific forms of human cancer." (PMID 23420765, 2013). "Upstream sensors like ZBP1, AIM2, and RIPK1, along with regulators identified in cancer-related PANoptosis studies, such as IRF1, ADAR, MAP3K7, and NFS1, were also incorporated for their significant regulatory roles." (PMID 39901195, 2025). "As expected, given its role in regulating IRF1 expression and the IFN response, CARINH is implicated in various cancers." (PMID 41283334, 2025).
cancer (continued). "In A549 cancer cells, the conditioned medium from NK-92 cells caused the phosphorylation of STAT1 at Tyr701, as well as the upregulation of the IRF1 and CASP1 proteins, which is consistent with the activity of IFNγ." (PMID 40512405, 2025). "In fibroblasts cocultured with endothelial cells, we observed significant upregulation of genes associated with cancer progression (MALAT1, NEAT1), vascular endothelial growth factor (VEGFA), and proinflammatory cytokines (NCOA3, IRF1)." (PMID 39805002, 2025). "Previous studies have shown that baicalein induces the expression of DDIT4 and IRF-1 (Interferon regulatory factor-1), leading to inhibition of mTOR signaling in other cancer types." (PMID 41303544, 2025). "Both IFN-α/β and IFN-γ activate JAK-STAT signaling to drive PD-L1 transcription by IRF1 in various cell types, including immune cells and cancer cells." (PMID 40920828, 2025). "For example, CHIP acts as a chaperone for IRF-1, a TF involved in cancer progression, to promote IRF-1 stability in unstressed cells but functions as an E3 ligase to trigger ubiquitination-dependent degradation of IRF-1 under stress conditions." (PMID 41028522, 2025). "The role of IRF1 in cancer progression is currently a topic of debate, contingent upon the specific type of cancer." (PMID 40025540, 2025). "Collectively, these findings highlight how YTHDFs modulate cancer immunity by influencing IFN‐γ signaling through IRF1 regulation, suggesting their viability as therapeutic targets in cancer immunotherapy." (PMID 39587835, 2025). "YTHDF1, along with YTHDF2 and YTHDF3, redundantly suppresses the IFN‐γ response by destabilizing IRF1 mRNA, suggesting that these proteins can serve as viable therapeutic targets in cancer immunotherapy." (PMID 39587835, 2025). "Interferon regulatory factor 1 (IRF1) is a protein that regulates many different biological processes, including the response to cancer." (PMID 38169587, 2024). "In contrast, even though we did not determine the detailed mechanism, DRG2 depletion enhanced STAT1/IRF1 signaling pathway and the expression of PD-L1 in cancer cells after IFN-γ treatment." (PMID 38802348, 2024). "This process involves upregulation of interferon regulatory factor-1 (IRF-1), linking embryonic developmental pathways to cancer progression." (PMID 39858295, 2024). "These investigations showed that IRF1 is a dual-edged sword that can increase cancer immune evasion by upregulating PD-L1 and promoting antitumor effects." (PMID 38789431, 2024). "Initially identified as a transcriptional regulator of interferon genes in cancer, IRF1 is required for Th1 polarization in NK cells, CD8+ cells, and M1 macrophages." (PMID 39201507, 2024). "This identifies IRF1 as an upstream regulator of PANoptosis to induce cell death, serving as a potential therapeutic target in cancer." (PMID 38169587, 2024). "Having seen a moderate correlation between CIITA and IRF1 in the bulk RNAseq data, we examined this in the snRNAseq, but found a more modest correlation between CIITA and IRF1 expression within cancer cells (R = 0.26, p < 0.001, CS-CORE)." (PMID 39025846, 2024). "Collectively, these observations indicate that ATXN3 promotes IFN-γ–induced PD-L1 transcription at least partially through the stabilization of its transcriptional factor IRF1 in cancer cells." (PMID 38038129, 2023). "verified that IFN-γ treatment induces cancer cell ferroptosis through the STAT1/IRF1/ACSL4 axis in hepatocellular carcinoma." (PMID 38288118, 2023).
cancer (continued). "Our analysis of the Sequence Read Archive (SRA), Gene Expression Omnibus (GEO), and Asian Cancer Research Group (ACRG) databases showed that TRIM28 is positively associated with PD-L1, TBK1, and IRF1 at the transcriptional level." (PMID 37357254, 2023). "In further support of this postulate, we found that Irf1−/− HSCs displayed enrichment of the “Pathways in cancer” gene set." (PMID 37889967, 2023). "Lastly, we assessed the importance of SPOP for IRF1 degradation in non-cancer-derived cells, and across species." (PMID 37622993, 2023). "Another class of genes we examined was that of immune checkpoint-regulated genes, which include IFNGR1 and IRF1 (both of which are important for T cell recognition of cancer cells)." (PMID 37394010, 2023). "With the action of IFN-γ, the activation of JAK1/2 and phosphorylation of STAT1 increase the expression of IRF1 on cancer cells." (PMID 38288118, 2023). "IRF1 has been shown to have roles in apoptosis, inflammation, cell growth and polarization, oncogenesis, and cancers." (PMID 38390290, 2023). "We also observed that TRIM28 expression is positively correlated with PD-L1, TBK1, and IRF1 levels in various cancers." (PMID 37357254, 2023). "We show that IRF1-based stratification identifies distinct cancer-related signatures in patient subgroups." (PMID 37889967, 2023). "IFN-γ exerts its critical role in cancer through the JAK/STAT1/interferon regulatory factor 1 (IRF-1) pathway." (PMID 35279217, 2022). "The excellent extrapolation of this generalized model to other cancer types for which fewer data are available provides confidence that the TFs IRF1, STAT1, NFKB, and BRD4 are in general dominant regulators of CD274 expression." (PMID 35289334, 2022). "Some studies have revealed that IRF-1 has antitumor effects via apoptosis and the cell cycle in human cancer." (PMID 35677632, 2022). "Collectively, these findings show that RAD51 inhibition-mediated IRF1 upregulation, a downstream component of ATR/Chk1 signaling, is a critical mechanism underlying PD-L1 expression regulation in cancer cells." (PMID 35646698, 2022). "The final model was highly significant (p = 2.2e−16), and for all three cancer types IRF1 was identified as a significant explanatory variable for CD274 expression (left 3 columns)." (PMID 35289334, 2022). "IRF1 was shown to play a critical role in the development of several types of cancer, such as cervical, breast, hepatocellular, prostate, colorectal, and pancreatic ductal adenocarcinoma." (PMID 36313570, 2022). "IRF1 represents a crucial transcriptional regulator of the IFNγ-response and recent findings on human cancers identified IRF1 as a central hub in cancer immunity." (PMID 34220848, 2021). "Using multicolour immunofluorescence analysis, we were able to validate the co-expression of γH2AX, IRF-1, and membrane PD-L1 in seven UC patients with colitic cancer and dysplasia." (PMID 34158547, 2021). "Multicolour immunofluorescence staining validated γH2AX/IRF-1/PD-L1 co-expression in colitic cancer tissue sections." (PMID 34158547, 2021). "Data analysis of scRNAseq pan-cancer dataset confirmed the existence of a CXCL10+IRF1+ STAT1+ M1-type Mφ across human cancers displaying activation of antigen presenting and cross presentation gene programs." (PMID 34220848, 2021). "IRF1 plays a crucial role in type I IFNs signaling and immunity as revealed by the involvement of IRF1 in various diseases, including cancer." (PMID 34462421, 2021). "Here, we uncover a MAPK/IRF1-mediated transcriptional reprogramming of senescent cancer cells that survive drug treatment." (PMID 34535668, 2021). "The anti-tumorigenic role of interferon regulatory factor 1 (IRF1) has been reported in several types of cancer, by regulating genes related to PD-L1, DNA damage, apoptosis, and lymphocyte differentiation, also interacting multiple signaling pathways." (PMID 34277600, 2021).